SLC25A6 (solute carrier family 25 member 6)
Description:
ADP:ATP antiporter that mediates import of ADP into the mitochondrial matrix for ATP synthesis, and export of ATP out to fuel the cell (By similarity). Cycles between the cytoplasmic-open state (c-state) and the matrix-open state (m-state): operates by the alternating access mechanism with a single substrate-binding site intermittently exposed to either the cytosolic (c-state) or matrix (m-state) side of the inner mitochondrial membrane (By similarity). In addition to its ADP:ATP antiporter activity, also involved in mitochondrial uncoupling and mitochondrial permeability transition pore (mPTP) activity. Plays a role in mitochondrial uncoupling by acting as a proton transporter: proton transport uncouples the proton flows via the electron transport chain and ATP synthase to reduce the efficiency of ATP production and cause mitochondrial thermogenesis (By similarity). Proton transporter activity is inhibited by ADP:ATP antiporter activity, suggesting that SLC25A6/ANT3 acts as a master regulator of mitochondrial energy output by maintaining a delicate balance between ATP production (ADP:ATP antiporter activity) and thermogenesis (proton transporter activity) (By similarity). Proton transporter activity requires free fatty acids as cofactor, but does not transport it (By similarity). Also plays a key role in mPTP opening, a non-specific pore that enables free passage of the mitochondrial membranes to solutes of up to 1.5 kDa, and which contributes to cell death. It is however unclear if SLC25A6/ANT3 constitutes a pore-forming component of mPTP or regulates it (By similarity).
Synonyms: ANT 2; ANT 3; AAC3; ANT3; ANT3Y; MGC17525; ANT
Tractability: Antibody: UniProt predicts a signal peptide or a membrane-spanning region. PROTAC: ubiquitination databases record sites on it; its protein half-life has been measured; a small molecule that binds it is known.
Target class: Electrochemical transporter; Transporter; SLC25 family of mitochondrial transporters; SLC superfamily of solute carriers
Gene: Protein-coding gene on chromosome X (1,386,133 to 1,392,929, reverse strand). Ensembl gene ENSG00000169100.
Subcellular location: Mitochondrion inner membrane; Membrane
Subcellular location (Human Protein Atlas): Mitochondria
Pathways (Reactome):
Disease: Influenza Virus Induced Apoptosis; Vpr-mediated induction of apoptosis by mitochondrial outer membrane permeabilization
Metabolism of proteins: Mitochondrial protein degradation
Protein localization: Mitochondrial protein import
Transport of small molecules: Transport of nucleosides and free purine and pyrimidine bases across the plasma membrane
Gene Ontology:
Molecular function: protein binding; ATP:ADP antiporter activity
Biological process: mitochondrial ATP transmembrane transport; regulation of mitochondrial membrane permeability; mitochondrial ADP transmembrane transport; transmembrane transport
Cellular component: membrane; mitochondrion; nucleus; mitochondrial inner membrane; mitochondrial permeability transition pore complex; TIM23 mitochondrial import inner membrane translocase complex
Homologues: Orthologues: chimpanzee SLC25A6 (100% identical), dog SLC25A6 (99% identical), pig SLC25A6 (98% identical), zebrafish slc25a6 (91% identical), macaque SLC25A6 (88% identical). Paralogues in human: SLC25A5 (92% identical), SLC25A4 (88% identical), SLC25A31 (71% identical), SLC25A13 (31% identical), SLC25A12 (30% identical), SLC25A43 (29% identical), SLC25A32 (28% identical), SLC25A16 (27% identical), SLC25A25 (26% identical), SLC25A29 (26% identical), SLC25A14 (26% identical), SLC25A36 (26% identical), and 37 more.
Diseases named in the same sentence as SLC25A6 in open-access papers:
SLC25A6 is named in the same sentence as 24 diseases in open-access papers, as found by Europe PMC text mining. Sharing a sentence is not in itself a finding about the gene and the disease. The quoted sentences say what the papers report.
ovarian carcinoma (2 papers, 2022 to 2025). A malignant neoplasm originating from the surface ovarian epithelium. "The analysis based on CCLE data suggested that some members of SLC25 family were highly expressed in breast, colorectal, stomach, liver, lung, and ovarian cancer cells, including SLC25A5, SLC25A6, and SLC25A8." (PMID 36254139, 2022).
Ataxia (1 paper, 2025). Ataxia refers to impaired coordination of voluntary muscle movement. "Altered abundance of SLC25A6 has been associated with ataxia, a neurological disorder characterized by impaired coordination, balance, and speech, which is also a recognized clinical manifestation of rabies." (PMID 41441337, 2025).
colorectal cancer (1 paper, 2026). A primary or metastatic malignant neoplasm that affects the colon or rectum. "Via single-cell monitoring using a caspase-3 activity indicator, we identified SLC25A6 as a key mediator of GMI-induced apoptosis in colorectal cancer cells." (PMID 42020360, 2026).
cytomegalovirus infection (1 paper, 2021). A herpesvirus infection caused by Cytomegalovirus. "SLC25A6 is downregulated in human cytomegalovirus infection and associated with influenza virus–induced apoptosis." (PMID 34379666, 2021).
glioma (1 paper, 2023). A benign or malignant brain and spinal cord tumor that arises from glial cells (astrocytes, oligodendrocytes, ependymal cells). "The solute carrier family 2 facilitated glucose transporter member 1 (SLC2A1), and the solute carrier family 25 members (SLC25A6) transcripts and proteins were up-regulated in glioma versus normal brain tissues." (PMID 37762371, 2023).
leukemia (1 paper, 2016). A malignant (clonal) hematologic disorder, involving hematopoietic stem cells and characterized by the presence of primitive or atypical myeloid or lymphoid cells in the bone marrow and the blood. "Interestingly, SLC25A6 was downregulated in several cancer cell lines upon treatment with camptothecin, including the leukemia cell lines HL-60 and K562, suggesting that reduced levels of SLC25A6 may aid in conferring resistance to camptothecin-induced apoptosis." (PMID 27655702, 2016).
melanoma (1 paper, 2025). A malignant, usually aggressive tumor composed of atypical, neoplastic melanocytes. "Similarly, in melanoma cells, SLC25A6 overexpression reduces cell viability, activates the cleavage of c-lamin A and PARP, and triggers cell death." (PMID 40841355, 2025).
osteosarcoma (1 paper, 2025). A usually aggressive malignant bone-forming mesenchymal neoplasm, predominantly affecting adolescents and young adults. "Similarly, studies have demonstrated that EFHD1 inhibits mPTP opening and enhances mitochondrial function through SLC25A6, reducing mitochondrial Cyt c release and promoting the proliferation and chemoresistance in osteosarcoma." (PMID 40841355, 2025).
ovarian serous cystadenocarcinoma (1 paper, 2022). A malignant serous cystic epithelial neoplasm arising from the ovary. "SLC25A6 mutation made significant effect on its expression in ovarian serous cystadenocarcinoma." (PMID 36254139, 2022).
spinocerebellar ataxia (1 paper, 2025). "Solute Carrier Family 25 Member 6 (SLC25A6), one of the proteins identified in the spinocerebellar ataxia pathway, functions as a mitochondrial carrier protein that mediates ADP/ATP exchange across the inner mitochondrial membrane." (PMID 41441337, 2025).
uveal melanoma (1 paper, 2022). A melanoma derived from melanocytes of the uveal tract. "Among them, SLC25A6 was most correlated with Macrophage M1 in uveal melanoma (r = −0.68, P = 1.9e − 0.5)." (PMID 36254139, 2022). "SLC25A6 was most correlated with macrophage M1 in uveal melanoma." (PMID 36254139, 2022).
cancer (10 papers, 2016 to 2026). A tumor composed of atypical neoplastic, often pleomorphic cells that invade other tissues. "For example, the divergent expression of RBP1 and SLC25A6, which is a cancer diagnostic, was observed in our dataset." (PMID 34121116, 2021). "Meanwhile, PC1 negatively associated genes included FLNA, ARF5, and SLC25A6, suggesting its connection to cancer development." (PMID 32231683, 2020). "Upregulation of SLC25A6 expression induced by the glutaminase inhibitor CB-839 sensitized cancer cells to the Bcl-2 inhibitor ABT-199." (PMID 42020360, 2026). "The phosphorylated RIPK1, in turn, represses the expression of SLC25A6, result in a transient increases in mitochondrial transmembrane potential (ΔΨm), which is highly related to cancer malignancy." (PMID 38149248, 2023). "The protein expression of SLC25A4, SLC25A5, and SLC25A6 was consistent in top 10 common cancer types." (PMID 36254139, 2022). "SLC25A6 results significantly upregulated in 7 cancer tissues and significantly downregulated in 2 cancer tissues, out of the 21 “tumor vs. normal” tissue pairs." (PMID 33396658, 2020). "SLC25A5 (solute carrier family 25, member 5) is highly expressed in cancer cells, and SLC25A6 (solute carrier family 25, member 6) is an enzyme involved in exchanging ADP/ATP through mitochondrial membranes and its expression has been shown to induce apoptosis in cellular culture." (PMID 29509794, 2018). "Additionally, they compared the mitochondria of cancer to that of normal cells, showing a significant increase in IMM potentials and the number of transporters, including SLC25A5, which shares many features with SLC25A6, to be strongly overexpressed in different types of cancers." (PMID 37762371, 2023).
tumor (8 papers, 2016 to 2025). "In this study, we provide evidence that MRPL13 enhances mitochondrial function and promotes tumor progression in OC by inhibiting mPTP opening via SLC25A6." (PMID 40841355, 2025). "Timer2 analysis shows that SLC25A4, SLC25A5, and SLC25A6 genes are differentially expressed in 16, 12, and 9 tissues out of the available 21 “tumor vs. normal” tissue pairs, respectively." (PMID 33396658, 2020). "SLC25A6 plays a significant role in maintaining mitochondrial membrane permeability, regulating mitochondrial function, and inducing cell death, thereby influencing tumor progression." (PMID 40841355, 2025). "Being that several PAR genes are implicated to function as tumor suppressors, such as PPP2R3B, SHOX, SLC25A6, ASMT, and DHRSX, they serve as prime candidates for further investigation and may hold the greatest therapeutic promise." (PMID 27655702, 2016). "It has been shown that the upregulated hub MMRG genes BCL2, MAVS, FKBP8, NBR1, and SLC25A6 and their products can participate in regulating drug resistance of tumour cells and the antitumour immune response and may be associated with the activation of inflammatory signalling pathways." (PMID 41463291, 2025). "In macrophages from tumor samples, two NPA genes, GLUL and SQSTM1, were found to be up-regulated, while SLC25A6 exhibited down-regulation." (PMID 38149248, 2023). "On the counterpart, 40435_at (SLC25A6), 33614_at (RPL18A, RPL18AP3), and 1657_at (PTPRR) are down-regulated (high expression values in normal class and low expression values in tumor class)." (PMID 33375940, 2020). "Similar to our findings, studies have shown that Mortalin can regulate mitochondrial membrane permeability and membrane potential by inhibiting the interaction between SLC25A6 and CypD, which suppresses mPTP opening, ultimately promoting the survival of BRAF-mutant tumor cells." (PMID 40841355, 2025). "ST1926 treatment down-regulated a group of oncogenic proteins (SLC2A1, SLC25A6, CBX3, DEK, DDX39B) and up-regulated a group of presumably tumor-suppressing proteins (PEBP1, HspBP1); PADI2 and CMPK1, of unknown function in GBM, were also up-regulated." (PMID 37762371, 2023). "Although the functions of SLC25A6 in hematopoiesis or leukemogenesis are not well characterized, these data indicate that it may serve as a tumor suppressor through its role in activating apoptosis." (PMID 27655702, 2016). "However, the deletion leading to the fusion of P2RY8 and CRLF2 also results in the deletion of several genes (P2RY8, CSF2RA, IL3RA, SLC25A6, and ASMTL) whose potential roles as tumor suppressors should not be discounted." (PMID 27655702, 2016).
infection (1 paper, 2018). The state of being infected such as from the introduction of a foreign agent such as serum, vaccine, antigenic substance or organism. "At the first stage of infection, SLC25A6, which has low acetylation activity and DNA methylation activity (p-value = 1.14 × 10−2), is repressed by human miR1244-1 and reduces transcriptional regulation via TFs, ESR1 and MYC." (PMID 30133498, 2018). "Furthermore, the low activity of MYC at the first infection stage affects the low expression of SLC25A6, which suffers from the repression of human miR1244-1, the transcriptional silence of DNA methylation (p-value = 1.14 × 10−2), and the acetylation by acetyltransferase protein KAT5." (PMID 30133498, 2018).
myopathy (1 paper, 2022). A disease of the muscle in which the muscle fibers do not function properly. "Gene expression levels of mitochondrial ion transporters, including VDAC1,2,3, SLC25A4, and SLC25A6, were not significantly changed, though all appeared elevated in the myopathy-derived skin fibroblasts." (PMID 35216315, 2022).
SLC25A6 also shares sentences with these, for which no sentence is quoted: prostate carcinoma (2 papers); Alzheimer disease (1); autoimmune disease (1); Hepatitis B (1); neurological disorder (1); Obesity (1); pancreatic cancer (1); Parkinson disease (1); short QT syndrome (1).